TRPM2 (transient receptor potential cation channel subfamily M member 2)
Diseases named in the same sentence as TRPM2 in open-access papers (continued):
Sharing a sentence is not in itself a finding about the gene and the disease.
cancer (continued). "H2O2 secreted by neutrophils relies on the Ca2+ channel to kill cancer cells, which regulates the expression of transient receptor potential cation channel subfamily M member 2 (TRPM2) to inhibit cancer-cell proliferation." (PMID 36230676, 2022). "Transient receptor potential channel melastatin 2 (TRPM2) is highly expressed in cancer and has an essential function in preserving viability through maintenance of mitochondrial function and antioxidant response." (PMID 35428820, 2022). "TRP channels implicated in mechanotransduction mechanisms that regulate cancer cell migration, invasion and metastasis include, among others, TRPC1, TRPC5, TRPM2, TRPM7, TRPM4, TRPV2 and TRPV4." (PMID 36158191, 2022). "These works reinforce the concept that TRPM2 inhibition by acidic pHe and activation by hypoxic conditions represent a protective mechanism for cancer cells." (PMID 35806388, 2022). "Concerning the TRPM family, the main channels involved in cancer therapy resistance include TRPM2 and TRPM8." (PMID 35207698, 2022). "For example, the expressions of TRPM2, TRPA1, and TRPM8 were associated with patient survival in 22, 16, and 19 cancer types, respectively." (PMID 35614079, 2022). "TRPM2 exerts this effect in particular by protecting cancer cells from oxidative stress by increasing their antioxidant defence." (PMID 35806388, 2022). "The increased expression of TRPM2 in malignant cells is consistent with its demonstrated role in promoting cancer cell proliferation and survival." (PMID 36446940, 2022). "Neutrophils can eliminate cancer cells through ROS-dependent killing, which induces lethal Ca2+ influx in target cells, dependent on transient receptor potential melastatin 2 (TRPM2) that is highly expressed in cancer cells." (PMID 36031601, 2022). "The knockdown of TRPM2 enhanced the anti-cancer effects of doxorubicin to decrease PyK2 phosphorylation." (PMID 36555115, 2022). "Other Ca2+-toolkit proteins implicated in various cancers include calcineurin, SERCA pumps, SPCAs, PMCAs, the IP3R, RyRs, STIM proteins, T-Type VGCCs, TRPC1, TRPC3, TRPC6, TRP ion channel melastatin 2 (TRPM2), TRPM7 and TRPM8." (PMID 36046118, 2021). "Next, we investigated the prognostic value of TRPM2 in different cancers using GEPIA and the Kaplan–Meier plotter platform." (PMID 35071322, 2021). "In order to examine the association between TRPM2 and clinical features, we assessed the multiple clinical prognostic values of TRPM2 in various cancers using the TIDISB database." (PMID 35071322, 2021). "In the current study, we first explored the correlation between the mRNA level of TRPM2 and the prognosis of patients with different cancers across public databases." (PMID 35071322, 2021). "Other studies with prostate, oral squamous, and breast cancer cells have provided evidence that, in these cancer cells, some TRPM2 protein is present in the nucleus." (PMID 34439491, 2021). "TRPM2 expression in cancer cells was mostly reported to correlate with poor prognosis, as shown in neuroblastoma, squamous cells carcinoma, T-cell leukemia, breast, gastric, lung, pancreatic and prostate cancer cell lines and in patient samples." (PMID 32887220, 2020). "In cancer cells, the role of TRPM2 as a plasma membrane ion channel is less important because of the internalization and nuclear localization of TRPM2." (PMID 32423430, 2020). "Among other things, it has been shown that TRPM2 is involved in cell migration and cell death, which are the key processes of cancer cell death." (PMID 32423430, 2020). "TRPM2 inhibition enhances death in cancer by impairing cellular antioxidant defenses and increasing ROS to cytotoxic levels." (PMID 31575956, 2019). "This would contribute to cancer cell death by increasing the influx of Ca2+ into the cell through TRPM2 channel activation." (PMID 30984336, 2019). "PAX and RESV increased overloading Ca2+ entry through TRPM2 channel activation to promote cancer cell death." (PMID 30984336, 2019).
cancer (continued). "The preponderance of data in cancer models support the concept that TRPM2 expression and function preserves cell viability." (PMID 31575956, 2019). "TRPM2-mediated GC migration/invasion was also found associated with an alteration in the regulation of EMT, an essential process during cancer metastasis." (PMID 30862883, 2019). "Metabolomics analysis was used as a second approach to study the impact of TRPM2 depletion in cancer metabolism." (PMID 31575956, 2019). "It is well known that increased mitochondrial ROS activation due to the activation of TRPM2 channels in cancer cells results in cell death and apoptosis." (PMID 31780732, 2019). "Here, the function of TRPM2 in modulation of oxidative stress in cancer was examined by exploring its role in generation of the antioxidant cofactors GSH and NAPDH, and regulation of expression of the transcription factor Nrf2." (PMID 31575956, 2019). "To date, the impact of TRPM2 activation on various signaling pathways in cancer cells survival has been studied." (PMID 30862883, 2019). "In many non-cancer models, TRPM2 has also been shown to preserve cell viability; for example, it protects the hearts of mice from ischemia/reperfusion injury." (PMID 31575956, 2019). "Among many ion channels, TRPM2 is emerging as a new potential therapeutic target in controlling cancer progression." (PMID 30862883, 2019). "The work here confirms the importance of calcium influx through TRPM2 in activation of Pyk2 and modulation of cell viability in cancer." (PMID 30020827, 2018). "Together, these results establish novel mechanisms for impaired cell survival and reduced mitochondrial function in TRPM2-inhibited cancer cells, particularly after doxorubicin treatment which increases oxidative stress." (PMID 30020827, 2018). "Transient receptor potential melastatin channel subfamily member 2 (TRPM2) has an essential function in cell survival and is highly expressed in many cancers." (PMID 30020827, 2018). "In several other pathological models mediated through oxidative stress, TRPM2 has been shown either to promote survival, as in many cancer models, or in some, enhance cell death." (PMID 30020827, 2018). "Messenger RNA data of lymphohematopoietic cancer lines suggest a correlation between expression of the cation channel TRPM2 and the antiapoptotic protein Bcl-2." (PMID 26839633, 2016). "To investigate the role of TRPM2 in carcinoma, we used the human tongue squamous cell lines, namely SCC-9 and SCC-25 cells, and the non-tumorigenic oral epithelial cell line HIOEC as the control." (PMID 28008929, 2016). "TRPM2 therefore appears to be a unique target in multiple cancers, where its pharmacologic inhibition can potentially provide an innovative strategy to selectively eradicate the tumors associated with those types of cancers." (PMID 26178079, 2015). "TRPM2 isoforms were shown to be overexpressed in several cancers, including melanoma, breast, and lung cancer." (PMID 26178079, 2015). "Activation and/or upregulation of TRPM2, NOX2, and PARP-1 have been linked to many cancers." (PMID 40722879, 2025). "Moreover, TRPM2 inhibitor‐based antibody‐drug conjugations (ADCs) or targeted nanoparticle drug delivery of TRPM2 inhibitors are other options for TRPM2‐targeted cancer therapy via reducing its systemic effects." (PMID 39044361, 2024). "Accordingly, targeting TRPM2 is a potentially promising strategy for overcoming and preventing acquired resistance to osimertinib, warranting further study in this direction including the development of cancer therapy‐optimized TRPM2 inhibitors." (PMID 39044361, 2024). "This new knowledge strongly supports TRPM2 as an important target for cancer therapy as well." (PMID 39044361, 2024). "On the other hand, increased levels of nuclear TRPM2 during the advanced stages of cancer may stimulate tumorigenesis." (PMID 37507867, 2023).
cancer (continued). "In some cancers, TRPM2 has a protective role via reducing oxidative stress, inflammation, and chromosomal instability, although in other cancers it may promote tumor progression." (PMID 37408210, 2023). "Through a series of bioinformatics analyses based on the publicly accessible database, we explored the mRNA expression of TRPM2 in pan-cancer and corresponding normal tissues, and the correlation between TRPM2 expression and survival prognosis and immune microenvironment." (PMID 37608401, 2023). "Thus, it is exceptionally valuable to explore more deeply the molecular mechanisms and immunoregulatory roles of TRPM2 in the pan-cancer dataset, so that new strategies can be developed for precision cancer therapy." (PMID 37569287, 2023). "Evidence thus suggests that targeting TRPM2 may be a novel therapeutic approach for the treatment of several cancers." (PMID 37445615, 2023). "However, in cancer cells, TRPM2 antagonism produced decreases in cell growth and increases in cell death." (PMID 37445615, 2023). "Based on the discussion of the available data, it can be concluded that TRPM2 may be a unique therapeutic target in the treatment of several types of cancer." (PMID 37337283, 2023). "TRPM2 cellular localization and protein expression levels appear to be unique in cancer cells." (PMID 37445615, 2023). "Various cancers showed high TRPM2 expression, including gastric 15, prostate 16, lung 17, bladder 41, and breast 42 cancer, suggesting it may play a certain role in carcinogenesis process." (PMID 36619219, 2023). "Targeting the TRPM2 function could, therefore, represent a tipping point that can be exploited for improved cancer therapy." (PMID 37576339, 2023). "The results suggested that DNA hypermethylation exerted a negative association with the expression level of TRPM2 in almost all cancer types, especially in PRAD and COAD." (PMID 37569287, 2023). "The genetic alterations of TRPM2 in various cancers from the TCGA database were obtained." (PMID 37569287, 2023). "In addition, we provide a comprehensive overview of the current knowledge of TRPM2 signaling pathways in cancer, including its functions in bioenergetics, oxidant defense, autophagy, and response to anticancer drugs." (PMID 37576339, 2023). "Does the role for TRPM2 in cancer cells entail its function as an ion channel?" (PMID 37445615, 2023). "Moreover, further studies should be carried out to implement targeting of TRPM2 as an anti-cancer therapeutic strategy." (PMID 37569287, 2023). "In particular, TRPM2 exhibited upregulation in six cancer types." (PMID 35614079, 2022). "Neutrophils secrete H2O2, which activates TRPM2 expressed on cancer cells’ surfaces." (PMID 35806388, 2022). "TRPM2 is widely considered as a potential therapeutic target, due to its crucial role in sustaining mitochondrial function, cell proliferation, and tumor metastasis in several types of cancers." (PMID 35207698, 2022). "Increased E2F1 and FOXM1 in cancers with high levels of TRPM2 may contribute to transcriptionally increased expression of α1, β1 and β5 integrins, and greater migration and invasion." (PMID 36446940, 2022). "There were eight favorable prognostic genes and six poor prognostic genes incorporated in this signature, and a variety of OSRGs such as CD38, FOXO1, HGF, IL18BP, and TRPM2 were closely involved in the previous studies regarding cancer subtypes and immune landscape." (PMID 36561981, 2022). "The results showed that TRPM2 was highly expressed in a majority of cancers." (PMID 35071322, 2021). "There were many articles reported the role of TRPM2 in various cancer in recent years." (PMID 34099637, 2021). "Klumpp found that the increased level of TRPM2 could promote Bcl (+) T lymph cell in strengthening the ability of DNA repair and cancer cell survival in T cell leukemia patients via P2Y6/P2Y12 pathway." (PMID 34099637, 2021). "The expression of TRPM2 was elevated in various cancers compared to that in normal tissues." (PMID 35071322, 2021).
cancer (continued). "In addition, the correlation between the level of TRPM2 and the degree of immune infiltration in various cancers were analyzed using the TIMER database and displayed as a heatmap." (PMID 35071322, 2021). "The authors suggest that TRPM2 located in the nucleus may be involved in the regulation of cell proliferation in cancer cells." (PMID 34439491, 2021). "Therefore, we analyzed the correlation of the level of TRPM2 with the immune infiltration level in various cancer types." (PMID 35071322, 2021). "TRPM2 is one ion channel that can be altered to increase apoptosis in cancer cells." (PMID 32423430, 2020). "Numerous TRPM2 proteins are translocated into the nucleus where they may have an important enzymatic function related to cancer cell proliferation." (PMID 32423430, 2020). "Recent studies suggest that TRPM2 may also regulate autophagy in pericytes and cancer cells by acting on the early step of autophagy, i.e. autophagic induction." (PMID 33244095, 2020). "In addition, we have shown that in the physiological state there is a positive relationship between PARP1, PARP2, and TRPM2, which is disturbed in cancer cells." (PMID 32423430, 2020). "After observing the increase in mitochondrial ROS and TRPM2 channel, we suspected whether cell death was increased in the cancer cells." (PMID 31780732, 2019). "Decreased levels of these two metabolites by TRPM2 depletion identifies additional pathways through which TRPM2 may modulate cancer progression." (PMID 31575956, 2019). "Excessive TRPM2 levels in cancer cells may have an enzymatic function in relation to cell proliferation." (PMID 30997980, 2019). "A significant amount of the TRPM2 proteins were located in the nuclei in cancer cells." (PMID 28008929, 2016). "In addition, mRNA data of hematopoietic and lymphoid tissue cancer cell lines of the Novartis and Broad Institute Cancer Cell Line Encyclopedia were queried for TRPM2 and Bcl-2 mRNA abundance." (PMID 26839633, 2016). "As there is growing evidence that specific types of cancer contain specific vulnerabilities, the presence of nuclear TRPM2 may therefore represent one such vulnerability." (PMID 25760245, 2015). "Based on the studies to date in three different types of cancer, it is possible that TRPM2 may have different localizations and different roles in various types of cancer." (PMID 26178079, 2015). "Future studies will be required to determine whether TRPM2 does indeed have novel roles in different types of cancer." (PMID 26178079, 2015). "It is thus possible that the unique member, TRPM2, may also have a novel role in human cancers as well." (PMID 25760245, 2015). "Collectively, efforts may be warranted to develop cancer‐optimized TRPM2 inhibitors." (PMID 39044361, 2024). "Thus, TRPM2 is a potential target for anti-cancer therapy in various tumors." (PMID 37608401, 2023). "Thus, the data from multiple types of cancers appear to support the hypothesis that TRPM2 has a unique role in cancer cells that most likely pertains to nuclear function." (PMID 37445615, 2023). "The role of TRPM2 in the nucleus of cancer cells is unknown." (PMID 37337283, 2023). "Next, we questioned whether TRPM2 could be used as a prognostic marker in cancers." (PMID 35071322, 2021). "Taken together with previous findings, TRPM2 expression promotes cell viability and modulates mitochondrial metabolism, cellular energetics, autophagy, glutamine metabolism and redox balance simultaneously, which make it an intriguing potential drug target in cancer." (PMID 31575956, 2019). "In addition to ADPR, TRPM2 is activated in primary and cancer cells by reactive oxygen species." (PMID 30984336, 2019). "Besides, some studies have investigated the role of TRPM2 in the development of human cancers." (PMID 26100964, 2015). "However, in cancer cells, TRPM2 appears to have a unique role." (PMID 26178079, 2015).
cancer (continued). "Recent studies suggest that the main channels involved in the oxidative stress-mediated cancer process are TRPML1, TRPA1, TRPM2 and TRPV1." (PMID 40813985, 2025). "In the following section, we provide an overview of how Piezo1/2, TRPC1, TRPC5, TRPM2, TRPM4, TRPM7, TRPV2 and TRPV4 affect cancer cell behavior." (PMID 36158191, 2022). "In particular, we discuss the roles of Piezo1/2, TRPC1, TRPC5, TRPM2, TRPM4, TRPM7, TRPV2, and TRPV4 in mechanosensing and cancer metastasis." (PMID 36158191, 2022). "Genetic alterations were correlated with transcriptome dysregulation of TRP genes, and we found that TRPM2, TRPM8, and TPRA1 showed extent dysregulation in cancer." (PMID 35614079, 2022). "In these studies, the expression levels of TRPV4, TRPM2, TRPM4, and TRPM8 in cancer tissues are significantly increased, which is consistent with our OV research." (PMID 35813831, 2022). "TRPM2, a highly Ca2+-permeable cation channel of the TRPM family, regulates cancer cell growth and survival." (PMID 35071322, 2021). "A recent study indicated that TRPM2 in cancer cells mediates H2O2-induced neutrophil cytotoxicity and the authors proposed that activation of the channel initiates cancer cell apoptosis." (PMID 32887220, 2020). "CELSR3, TRPM2, and TRIP13 are over-expressed in all the 13 cancers, TNXB is under-expressed in all the 13 cancers, KCNAB1 is over-expressed in KIRC but under-expressed in the other 12 cancers." (PMID 30729033, 2019). "However, the lack of plasma membrane TRPM2 and an elevated level of nuclei TRPM2 during the advanced stages of cancer may increase susceptibility to tumorigenesis." (PMID 28008929, 2016). "Actually, H2O2-induced Ca2+ influx through TRPA1, but not TRPM2, induces oxidative stress tolerance in cancer cells." (PMID 37478173, 2023). "The subcellular location of TRPM2 was not similar in cancerous and non-cancerous cells as a considerable extent of TRPM2 protein is located in the cancer cell’s nucleus." (PMID 37337283, 2023). "Our above results indicated that TRPM2 may play a role in an immune-dysregulated TME by affecting immune cell infiltration and communication between immune and cancer cells." (PMID 37569287, 2023). "In the tongue carcinoma (SCC) cell line SCC9, it was observed an enhanced expression of TRPM2 located at the nucleus of cancer cells, in contrast with non-malignant human tongue samples." (PMID 36844925, 2022). "Polymerase poly ADP-ribose (PARP) is involved in activation of TRPM2 through generation of ADPR and the role of PARP inhibitors, which may also modulate TRPM2 function in neurological diseases and in cancer, is under investigation." (PMID 35428820, 2022). "Additionally, TRPC1, TRPC5, TRPM2, TRPM4, TRPM7, TRPV2 and TRPV4 can independently induce EMT in cancer cells." (PMID 36158191, 2022). "Besides, TRPM2/PCLO was a co-occurring gene pair in the IFNGrGS score-low group, indicating a possible synergistic perturbation of different cancer-related biological processes." (PMID 34566988, 2021). "Since TRPM2 has mostly been investigated in noncancerous cells, less is known about the function of the TRPM2 cation channel in cancer cells." (PMID 25760245, 2015). "However, these protective effects that lead to cell survival due to TRPM2 antagonism have not precluded TRPM2 from being identified as a cancer target." (PMID 37445615, 2023). "TRPM2 has been reported as a survival predictor in various cancers but not in OC." (PMID 37608401, 2023). "Our studies may suggest disrupted signaling between TRPM2 and PARP genes in cancer cells." (PMID 32423430, 2020). "Thus, it is conceivable that the novel role for TRPM2 in cancer cells is the basis for the observation that inhibition of TRPM2 produces novel chemotherapeutic effects in cancer cells, with minimal deleterious effects in non-cancerous cells." (PMID 26178079, 2015).